RPTOR (regulatory associated protein of MTOR complex 1)
Diseases named in the same sentence as RPTOR in open-access papers (continued):
Sharing a sentence is not in itself a finding about the gene and the disease.
cancer (39 papers, 2010 to 2026). A tumor composed of atypical neoplastic, often pleomorphic cells that invade other tissues. "Only the CpG in the intron of RPTOR (cg08129331) was replicated and was also associated with a consistently lower methylation in the cancer group (p-value = 0.05 in Roos study)." (PMID 31149338, 2019). "In addition, RPTOR (Regulatory Associated Protein Of mTOR Complex 1) has been reported to play a key role in nutrient and insulin-sensing pathways regulating cell growth in cancer, while SLC43A2 has also been identified as a regulator of the mTORC1 complex in cancer studies." (PMID 41373473, 2025). "These miR-99 family members negatively regulate IGF1R or downstream protein synthesis signaling molecules, including MTOR and RPTOR in cancer cells, macrophages, and dermal cells." (PMID 35159261, 2022). "Based on the multiple lines of evidence, we highlight the CpG in the first intron of RPTOR (cg08129331) as a stronger potential pan-cancer biomarker as this specific CpG was replicated in the Roos data." (PMID 31149338, 2019). "The CpG in the intron of RPTOR (cg08129331), which was cancer-hypomethylated in Health ABC, also showed a similar hypomethylation in the Roos cohort at p-value = 0.05." (PMID 31149338, 2019). "In particular, we highlight CpG methylation in the RPTOR gene as a potential biomarker of cancer that awaits further validation." (PMID 31149338, 2019). "As illustrated in the results section, three interconnected proteins, ARFGEF1, PLD2, and RPTOR, were successively activated, stimulating the cancer driver mTOR SP." (PMID 29062084, 2017). "It is noteworthy that many genes within these pathways (e.g., AKT2, AKT3, CREBBP, MAPK1, GNAS, RPTOR) are already known to play relevant roles in cancer cell growth and proliferation, which could provide a plausible biological basis for such a link." (PMID 41226303, 2025). "RPTOR is upregulated in a variety of cancers and promotes tumor metastasis in various ways." (PMID 38163890, 2024). "Therefore, we made use of the Cancer Dependency Map by focusing on the genes encoding the mTOR components MTOR, RPTOR, and RICTOR." (PMID 37642941, 2023). "RPTOR is a key component in mTOR pathway, a cell-signaling pathway commonly deregulated in human cancer, which plays roles in mRNA translation, autophagy, cell growth and immune responses (it restricts proinflammatory and promotes an anti-inflammatory response)." (PMID 35163587, 2022). "Other distinguished species found were mTOR (3.6 × 10−4) and its regulator, RPTOR (1.05 × 10−3), critical for controlling cancer metabolism, and structural proteins such as microtubule-associated proteins 1B, 4, and RB (1.15 × 10−3; 1.78 × 10−3; 7.3 × 10−3, respectively)." (PMID 36293503, 2022). "Notably, integration of the BLV genome has been identified near the genes that play a role in cancer development, such as in the intergenic region of RTN4IPI and ATG5, and in the intron of the regulatory-associated protein of mTOR (RPTOR) in two B-cell lymphoma lines." (PMID 41596377, 2026). "RPTOR, mechanistic target of rapamycin kinase and MTOR associated protein (mTOR), LST8 homolog (MLST8) constitute the core subunits of the mammalian TORC1 complex which play an important role in controlling cell growth, survival and metabolism and is often deregulated in cancer." (PMID 29933410, 2018). "This suggested that RPTOR methylation may play an important role in the process of cancer." (PMID 29933410, 2018). "Database synthesis corroborated disease associations involving MTOR and its partners (e.g., TSC2, RICTOR, RPTOR, MLST8, AKT1 across selected carcinomas)." (PMID 41300706, 2025).
cancer (continued). "Compared with the control, the number of cancer cells passing through the BBB at days 1 and 3 was significantly higher in cells overexpressing RPTOR (OE) and lower in cells with RPTOR knockdown." (PMID 38163890, 2024). "Combined treatment with THZ531 and inhibitors of pathways regulated by these cancer relevant genes (EGFR, RPTOR, ATRIP) exerted synergic effects on HGSOC PDO viability." (PMID 37202753, 2023). "In the D5 (DAC stage), mTOR signaling (e.g., AKT2 and RPTOR) and EGFR signaling (e.g., EGFR and GSK3B) were overrepresented, implying the progression of cancer and tumor growth." (PMID 36991000, 2023). "As exemplified by EGFR and RPTOR, these new CDK12/13 target genes function in pathways that are actionable in HGSOC, as clinically approved inhibitors have shown efficacy in other cancer types." (PMID 37202753, 2023). "RPTOR, along with TSC2, is a part of the mTOR signaling pathway known to affect many different types of cancer." (PMID 33466343, 2021). "Although this analysis was carried out in only the 6 cancer cases, the correlations between deltaβ and time to diagnosis were significant for the CpGs in the promoter region of REC8, and introns of RPTOR and ZSWIM5." (PMID 31149338, 2019). "In terms of major cancer-related proteins among SM-specific hubs, NOTCH1, ARFGEF1, PLD2, and RPTOR were strongly aligned with hallmarks of NSCLC." (PMID 29062084, 2017). "The results confirmed the strong anti-cancer activity of cyclin-dependent kinase 12 and 13 (CDK12/13) inhibitors and the synergistic effect of THZ531 and pathway inhibitors (EGFR, RPTOR, ATRIP) regulated by cancer-related genes on the activity of HGSOC organoids." (PMID 38989138, 2024). "Further, to investigate this association, we evaluated the correlation between SESN2 and mTOR pathway-related markers, including RPTOR, MTOR, and RHEB, by analyzing RNA expression data from cancer patients using the Gene Expression Profiling Interactive Analysis (GEPIA) database." (PMID 32899752, 2020). "RPTOR, mTOR, and MLST8 constitute the core subunits of the mammalian TORC1 (mTORC1) complex which play a major role in the control of cell growth and metabolism and is often deregulated in cancer." (PMID 27799065, 2016). "This revealed that MTOR, and to a lesser extent RPTOR and RICTOR, are indispensable for the survival of the majority of cancer cell lines, regardless of MYC amplification status." (PMID 37642941, 2023).
tumor (17 papers, 2015 to 2025). "Several studies suggest that an abnormally-elevated expression of RPTOR may be closely associated with tumor metastasis." (PMID 38163890, 2024). "In the late AB subpopulation we also identified mutations in PIK3C2B and RPTOR, which may sensitize the tumor to a number of drugs that target the PI3K/Akt/mTOR signaling pathways." (PMID 25729435, 2015). "We proposed that the potential function of RPTOR and IMPDH2 in regulation of tumor immune cell infiltration, and their association with the cetuximab sensitivity is deserved to be further explored in the future." (PMID 38302471, 2024). "In the mouse and zebrafish models, the respective RPTOR interference applied to the tumor cells and the host revealed that RPTOR blockage significantly suppressed the BM progress." (PMID 38163890, 2024). "The findings provide novel insights into the role of RPTOR in tumor metastases." (PMID 38163890, 2024). "Accordingly, the protein expression of EIF4E3, RPTOR, and AKT1S1 were all significantly associated with the MGPS, suggesting the elevated RNA translation efficiency led by EIF4EBP1_pT37 could promote tumor cell proliferation." (PMID 36434634, 2022). "Taken together, this indicates that the mutated RPTOR may create a selective advantage and play an important role in the tumor progression, which in this case have led to parallel evolution on CNA level resulting in different copy number gains of the mutated RPTOR." (PMID 29130628, 2018). "Since the MOA agents listed for SOM meta-clades 21 through 24 have roles in DNA damage, defective CDKN2A, RPTOR and KRAS may contribute to chemosensitivity of tumor cell lines to these agents." (PMID 33909629, 2021).
infection (6 papers, 2017 to 2023). The state of being infected such as from the introduction of a foreign agent such as serum, vaccine, antigenic substance or organism. "Key genes including elongation initiation factor pathway genes, GSK3B, and regulatory associated protein of mTOR (RPTOR) genes that protect cells from infection were significantly downregulated in Native Hawaiians." (PMID 36450776, 2022). "RPTOR is a regulatory associated protein of mechanistic target of rapamycin, and involved in initiating T follicular regulatory cell differentiation by activating the TCF-1-Bcl-6 axis during immunization or infection." (PMID 32365959, 2020).
bacterial infection (2 papers, 2025). "In bacterial infections, the RPTOR protein is often upregulated, activating the mTORC1 pathway." (PMID 40724870, 2025).
hematological disease (1 paper, 2021). "Genes highlighted here in, such as PRDM16, PER3, NOM1 BAHCC1, ZNF423, SETD7, RPTOR, and others have been implicated in hematological disease development, progression or clinical outcome." (PMID 34200630, 2021).
RPTOR also shares sentences with these, for which no sentence is quoted: renal carcinoma (5 papers); glioma (4); cervical cancer (2); colon cancer (2); degenerative disc disease (2); hepatocellular carcinoma (2); ovarian carcinoma (2); prostate carcinoma (2); schizophrenia (2); adrenocortical tumors (1); age (1); autoimmune disease (1); B-cell CLL (1); B-cell lymphoma (1); cardiac diseases (1); cardiomyopathy (1); cardiovascular diseases (1); childhood ovarian dysgerminoma (1); chronic kidney disease (1); clear cell renal cell carcinoma (1); Cognitive impairment (1); cystic fibrosis (1); depression (1); diabetes (1); disc degeneration (1); gastric adenocarcinoma (1); glioblastoma (1); gout (1); heart failure (1); hyperuricemia (1).
A further 20 diseases each share a sentence with RPTOR in 1 paper.